SLC22A14 (solute carrier family 22 member 14)
Description:
Riboflavin transporter localized at the inner mitochondrial membrane of the spermatozoa midpiece, which is required for male fertility (By similarity). SLC22A14-mediated riboflavin transport is essential for spermatozoa energy generation and motility: riboflavin is the precursor of FMN and FAD, which are coenzymes of many enzymes in the TCA cycle (the citric acid cycle) in mitochondria (By similarity). Required for sperm motility and normal sperm flagellar structure (By similarity).
Synonyms: OCTL2; ORCTL4; OCTL4
Tractability: Small molecule: it belongs to a druggable protein family. Antibody: UniProt predicts a signal peptide or a membrane-spanning region; its Gene Ontology location is reachable by antibodies, with medium confidence.
Gene: Protein-coding gene on chromosome 3 (38,282,294 to 38,318,575, forward strand). Ensembl gene ENSG00000144671.
Subcellular location: Mitochondrion inner membrane; Cell projection, cilium, flagellum membrane
Subcellular location (Human Protein Atlas): Connecting piece; Mid piece; Principal piece; Perinuclear theca
Gene Ontology:
Molecular function: protein binding; riboflavin transmembrane transporter activity; transmembrane transporter activity
Biological process: riboflavin transport; transmembrane transport
Cellular component: mitochondrial inner membrane; membrane; sperm principal piece
Genetic constraint (gnomAD): Loss-of-function variants: 49 observed, 53.73 expected, observed/expected ratio (o/e) 0.91, 90% interval 0.72 to 1.16. The upper end of that interval is the gene's LOEUF score, 1.16, which puts it in group 5 of 6, group 1 being the genes least tolerant of losing a copy. Missense variants: 648 observed, 744.29 expected, observed/expected ratio (o/e) 0.87, 90% interval 0.81 to 0.93. Synonymous variants: 308 observed, 310.34 expected, observed/expected ratio (o/e) 0.99, 90% interval 0.9 to 1.09.
Homologues: Orthologues: chimpanzee SLC22A14 (97% identical), macaque SLC22A14 (87% identical), dog SLC22A14 (67% identical), rat AABR07071731.1 (61% identical), mouse Slc22a14 (59% identical), pig SLC22A14 (59% identical), zebrafish si:dkey-166k12.1 (25% identical), zebrafish oatx (25% identical), Caenorhabditis elegans oct-1 (24% identical), Drosophila melanogaster Orct (23% identical), Drosophila melanogaster CG5592 (22% identical), Drosophila melanogaster Orct2 (22% identical), and 43 more. Paralogues in human: SLC22A13 (31% identical), SLC22A8 (28% identical), SLC22A2 (25% identical), SLC22A1 (25% identical), SLC22A6 (25% identical), SLC22A12 (24% identical), SLC22A3 (24% identical), SLC22A7 (24% identical), SLC22A5 (24% identical), SLC22A24 (24% identical), SLC22A11 (24% identical), SLC22A9 (23% identical), and 10 more.
Diseases named in the same sentence as SLC22A14 in open-access papers:
SLC22A14 is named in the same sentence as 8 diseases in open-access papers, as found by Europe PMC text mining. Sharing a sentence is not in itself a finding about the gene and the disease. The quoted sentences say what the papers report.
Infertility (3 papers, 2016 to 2024). "We investigated the physiological role of Slc22a14 using knockout mice and found that Slc22a14-deficient male mice showed severe infertility." (PMID 27811987, 2016). "Additionally, infertility in mice, particularly those with Slc22a14 (riboflavin transporter) knockout, is linked to triglyceride accumulation in sperm, coupled with notable deficiencies in fatty acid beta-oxidation." (PMID 39337684, 2024). "In infertility mice subjected to Slc22a14 (riboflavin transporter) knockout, triglycerides accumulate in sperm, and significant fatty acid β-oxidation deficiencies are observed." (PMID 36337197, 2022).
asthenospermia (2 papers, 2016 to 2021). "Whether this polymorphism is associated with male fertility is unknown, but future work should investigate the relationship between SLC22A14 polymorphism and the pathogenesis of asthenozoospermia or teratozoospermia in humans." (PMID 27811987, 2016).
male infertility (2 papers, 2016 to 2024). The inability of the male to effect fertilization of an ovum after a specified period of unprotected intercourse. "More interestingly, Slc22a14 is a candidate gene responsible for male infertility in oligotriche mutant mice." (PMID 27811987, 2016). "As described in the Introduction, Slc22a14 is a candidate gene responsible for male infertility in oligotriche (olt/olt) mutant mice." (PMID 27811987, 2016). "Knockout of Slc22a14 disrupts sperm FAO activity and leads to male infertility in mice." (PMID 39074078, 2024). "Slc22a14 is expressed specifically in male germ cells, and mice lacking the Slc22a14 gene show severe male infertility." (PMID 27811987, 2016).
SLC22A14 also shares sentences with these, for which no sentence is quoted: alopecia (1 paper); breast carcinoma (1); lung and (1); premature ovarian failure (1); teratozoospermia (1).